SMURF2 (SMAD specific E3 ubiquitin protein ligase 2)
Diseases named in the same sentence as SMURF2 in open-access papers (continued):
Sharing a sentence is not in itself a finding about the gene and the disease.
lung carcinoma (21 papers, 2014 to 2025). "Taken together, these data suggest that the low miR‐195 and miR‐497 expressions and high SMURF2 expression are associated with the biological process of tumorigenesis in lung cancer patients." (PMID 31581360, 2019). "In lung cancer, Smurf2 enhances epidermal growth factor receptor (EGFR) stability, contributing to resistance against TKI." (PMID 40978141, 2025). "On contrast, transient silence of Smurf1 and Smurf2 by si-RNAs promoted apoptosis in H1299 lung cancer cells." (PMID 37291499, 2023). "Inverse correlation between pHSP27 and Smurf2 was observed in the lung tissues of PF animals, an irradiated orthotropic lung cancer models, and PF tissues from patients." (PMID 36611161, 2023). "In order to confirm the results of enrichment analysis of NEDD4 family members-interacted proteins, we transfected plasmids of Smurf1, Smurf2 in A549 and H1299 lung cancer cells." (PMID 37291499, 2023). "The effects of SMURF2 on the biological behavior of lung cancer cell lines were investigated by performing cell proliferation, migration, and invasion analyses using the constructed cells with SMURF2 KD." (PMID 37497010, 2023). "Co-Immunoprecipitation (Co-IP), proximity ligation assay (PLA), chromatin immunoprecipitation (ChIP) and nude mice tumor-bearing model were applied to further clarify the role of SMURF2 in lung cancer." (PMID 37497010, 2023). "Four lung cancer cell lines, A549, H460, H1650, and H1395, were used to explore the relationship between SMURF2 and ID2 expression." (PMID 37497010, 2023). "We successfully identified and validated Smurf2 as both a common modulator of resistance and an actionable target in lung cancer." (PMID 35710591, 2022). "In summary, our study is the first to indicate the potential role of Smurf2 as a common modulator of resistance and to identify Smurf2 as a potential novel actionable target that can improve responses to both cisplatin and radiation therapy in lung cancer." (PMID 35710591, 2022). "Our results suggest that Smurf2 is a potential novel target and indicate a new mechanism of bortezomib-mediated sensitization to cisplatin and radiation therapy via Smurf2 inhibition in lung cancer." (PMID 35710591, 2022). "Of note, AIMP2 had a tumor suppressor activity on lung cancer cells by Smad ubiquitination regulatory factors 2 (Smurf2)." (PMID 34660690, 2021). "Despite it has been reported that Smurf2 is the target gene of miR-497 in lung cancer cells, miRNA profiles are tissue-specific." (PMID 33193708, 2020). "As expected, reduction of cell proliferation by miR‐195 or miR‐497 was restored by the overexpression of SMURF2, indicating that miR‐195 and miR‐497 inhibit cell proliferation by reducing SMURF2 levels in lung cancer cells." (PMID 31581360, 2019). "We demonstrated this possibility by performing invasion assay with Flag‐SMURF2; ectopically expressed SMURF2 increased the invasion ability of lung cancer cells reduced by the two miRNA in the presence of TGF‐β1." (PMID 31581360, 2019). "As those of lung cancer tissue and blood samples, miR‐195 and miR‐497 expressions were lower, whereas SMURF2 expression was higher in most lung cancer cell lines than in the controls." (PMID 31581360, 2019). "We previously demonstrated that fucoidan effectively inhibits cell growth and migration via induction of Smurf2-dependent ubiquitin degradation of TGFβ (TGF) receptors (TGFR) in lung cancer cells." (PMID 28332554, 2017). "A previous report indicated that SMURF2 mediated the ubiquitin-dependent degradation of Hsp27 in A549 lung cancer cells." (PMID 27136586, 2016). "We propose that one of the mechanisms for fucoidan-mediated inhibition of lung cancer in vivo and in vitro depends on promoting the ubiquitination and degradation of TGFRs via Smurf2/Smad7." (PMID 25149540, 2014).
lung carcinoma (continued). "In conclusion, these data suggest that SMURF2 downregulation promotes lung cancer cell proliferation, accelerates their migration and invasion, and may ultimately contribute to tumor progression." (PMID 37497010, 2023). "This hypothesis was tested by investigating the effects of SMURF2 on several cell cycle-related genes using KD or OE lung cancer cell lines (A549 and H460)." (PMID 37497010, 2023). "After transfection of NEDD4 family members Smurf1 and Smurf2, the lung cancer cells H1299 were subjected to cisplatin (a commonly used chemotherapy drug) treatment to detect the difference of apoptosis in relation to Smurf1 and Smurf2." (PMID 37291499, 2023). "Furthermore, our results of flow cytometric analysis suggested that both Smurf1 and Smurf2 suppressed apoptosis in H1299 lung cancer cells, which were in consistence with previous reports of the involvement of Smurf1 and Smurf2 in apoptosis." (PMID 37291499, 2023). "The high expression of Smurf2 could predict the poor prognosis of lung cancer, while the treatment of bortezomib can significantly down-regulate Smurf2 in lung cancer cells." (PMID 37795365, 2023). "Furthermore, we found that the small molecule proteasome inhibitor bortezomib significantly downregulated Smurf2 in lung cancer cells." (PMID 35710591, 2022). "We found that SMURF2 expression was increased in lung cancer." (PMID 31581360, 2019). "Therefore, we focused on the effects of miR‐195 and miR‐497 on the SMURF2 gene expression and their biological functions in lung cancer." (PMID 31581360, 2019). "Furthermore, miR‐195 and miR‐497 regulate SMURF2‐dependent TβRI ubiquitination and cause the activation of the TGF‐β signaling pathway in lung cancer cells." (PMID 31581360, 2019). "Similarly, Smurf2 stabilizes EGFR in lung cancer and cervical cancer, indicating that Smurf2 could be an oncogene in lung and cervical cancers." (PMID 40978141, 2025). "Furthermore, the overexpression of SMURF2 significantly inhibited lung cancer cell progression." (PMID 37497010, 2023). "Finally, we found that both Smurf1 and Smurf2 suppressed apoptosis in H1299 lung cancer cells." (PMID 37291499, 2023). "In addition, Smurf2 can be targeted and inhibited via miR-195 in lung cancer cells." (PMID 34267179, 2021). "Hence, it is possible that miR‐195 or miR‐497 could decrease invasiveness of lung cancer cells by suppressing the expression of SMURF2 gene directly, although TGF‐β signaling was activated." (PMID 31581360, 2019). "In addition, we examined miR‐195/497 and SMURF2 expression levels in lung cancer cell lines." (PMID 31581360, 2019). "However, it currently remains unknown whether these Smurf2 activities are pertinent to its tumor suppressor functions in lung cancer, and/or in other types of tumors." (PMID 30116722, 2018). "To further demonstrate the possible regulatory mechanisms of SMURF2 on ID2, we used MG132 and CHX to inhibit degradation and block synthesis in lung cancer cells." (PMID 37497010, 2023). "We demonstrated that miR‐195 and miR‐497 directly target SMURF2 with the luciferase assay and regulate TGF‐β signaling in lung cancer cells." (PMID 31581360, 2019). "Thus, our current findings indicate that fucoidan has great potential as a therapeutic intervention in controlling lung cancer and that the manipulation of the Smurf2-dependent UPP-mediated degradation of TGFR proteins may be an effective strategy for cancer patients." (PMID 25149540, 2014). "To determine the role of Smurf2 in lung cancer cell proliferation and resistance to cisplatin chemotherapy, we first efficiently knocked down Smurf2 protein expression in PC9 and A549 NSCLC cells using three individual siRNAs targeting Smurf2." (PMID 35710591, 2022).
lung carcinoma (continued). "Additionally, the putative targets of miR-497-5p including PSMD7, CCND3, SMURF2, and WNT7A increase chemoresistance in gastric cancer, acute myeloid leukemia, lung cancer and OSCC, respectively." (PMID 36703917, 2022). "Next, we explored the upstream of Smurf2 and validated miR-195 could target Smurf2 in ARPE-19 cells, which was also in agreement with the finding in lung cancer cells." (PMID 34267179, 2021). "Among them, SMURF1, MDM2, SMURF2, TRIM27, and NEDD4L are involved in lung cancer progression." (PMID 33264103, 2020). "In addition, fucoidan reduces tumor size in LLC1-xenograft male C57BL/6 mice and decreases tumor growth by modulating the TGFR/Smad7/Smurf2-dependent axis, leading to TGFR protein degradation and inhibition of lung cancer cell progression in vitro and in vivo." (PMID 31041568, 2019). "This study was identified a novel mechanism for the anti-tumor activity of fucoidan, namely decreasing tumor growth by modulating the TGFR/Smad7/Smurf2-dependent axis, leading to TGFR protein degradation and inhibition of lung cancer cell progression in vitro and in vivo." (PMID 31041568, 2019). "In addition, the authors demonstrated that knockdown of Smurf2 reduces the clonogenic survival and prolongs tumor latency in the mutant KRAS-driven tumors generated in nude mice with either human colon or lung carcinoma cells." (PMID 30116722, 2018). "Our finding that upregulated miR-128-3p in NSCLC cells simultaneously suppresses multiple negative regulators of β-catenin and TGF-β signalling, including Axin1, SFRP2, WIF1, SMURF2 and PP1c, provides unique insights in understanding the modulation of the β-catenin and TGF-β pathways in lung cancer." (PMID 28627514, 2017). "Here, we examined whether Smurf2 and/or Smad7 are involved in the processing step of the fucoidan-mediated UPP degradation of TGFR in lung cancer cells." (PMID 25149540, 2014). "Similarly, the amount of protein of SMURF2 and TRIM27 was also increased and that of SIX3 was decreased in lung cancer tissues compared with adjacent normal lung tissues, although we found that there was a significant correlation between the protein level of SIX3 and TRIM27, but not of SMURF2." (PMID 33264103, 2020). "However, it is not clear yet which miRNA regulate the abundance of SMURF2 in lung cancer." (PMID 31581360, 2019).
renal fibrosis (13 papers, 2013 to 2025). A final common manifestation of a wide variety of chronic kidney diseases characterized by glomerulosclerosis and tubulointerstitial fibrosis. "We also find that Ang II can induce an E3‐ligase, Smurf2, which can bind and degrade Smad7, thereby promoting Smad3‐dependent renal fibrosis and NF‐κB‐mediated renal inflammation." (PMID 32971570, 2020). "The expression of genes that promote renal fibrosis (Smad2, Smad3, Smad4, Shh, Dll1) was downregulated, while the expression of genes that inhibit renal damage (Smurf1, Smurf2, Smad1, Smad5, Smad6, Smad7) was increased in the WT+miPEP31 group (PEP1/2) compared with the WT+ cPEP (SCR1/2) group." (PMID 38992718, 2024). "Similarly, SMAD2 and SMAD7 are renoprotective in the course of renal fibrosis, wherein Smurf2 stimulates the degradation of SMAD2, resulting in weakened or repressed biological function." (PMID 35379779, 2022). "In addition, the loss of Smad7 expression also largely promotes TGF-β1-induced renal fibrosis and Smurf2/NF-κB-driven inflammation in mouse models of obstructive nephropathy and angiotensin II-induced hypertensive nephropathy 27-30." (PMID 34512167, 2021). "Moreover, inhibiting HSP90 activation prevents the development of renal fibrosis through the degradation of TβRII depending on Smurf2-mediation." (PMID 31275142, 2019). "Blockade of NF-κB-driven renal inflammation and TGF-β/Smad3-mediated renal fibrosis by preventing the Smurf2-mediated Smad7 degradation pathway may be mechanisms through which TSF inhibits type 2 DN." (PMID 26807792, 2016). "More significantly, we also found that inhibition of Smurf2-mediated ubiquitin degradation of Smad7 may be a central mechanism by which TSF suppressed both TGF-β/Smad3-mediated renal fibrosis and NF-κB-dependent renal inflammation in the diabetic kidney." (PMID 26807792, 2016). "Hence, the authors suggested that dysregulation of SMURF2 could contribute to the pathogenesis of renal fibrosis." (PMID 30696809, 2019). "Smad ubiquitination regulatory factor 2 (Smurf2), a ubiquitin ligase for Smad, plays a key regulatory role in the TGF-β signaling pathway during renal fibrosis, which is mainly dependent on the degradation of ubiquitinated Smad7 and Smad2." (PMID 34059951, 2021). "Smad7 is an inhibitory Smad that negatively regulates TGF-β/Smad-mediated renal fibrosis by facilitating degradation of TGF-β receptor-1 and Smads via the Smurf2 and arkadia-dependent ubiquitin-proteasome mechanism." (PMID 23301086, 2013). "The authors suggested that SMURF2-mediated ubiquitylation/degradation of SMAD7, SnoN, and Ski might potentiate TGF-β signaling, leading to renal fibrosis." (PMID 30696809, 2019). "We also identify that prevention of Smurf2-mediated Smad7 ubiquitin degradation, thereby inhibiting both TGF-β/Smad3-mediated renal fibrosis and NF-κB-dependent renal inflammation may be mechanisms associated with the beneficial effect of TSF on DN." (PMID 26807792, 2016).
colorectal cancer (10 papers, 2013 to 2025). A primary or metastatic malignant neoplasm that affects the colon or rectum. "In colorectal cancer, Smurf2 promotes the ubiquitination and degradation of carbohydrate response element-binding protein (chREBP), thereby reducing aerobic glycolysis and inhibiting cell proliferation." (PMID 40978141, 2025). "SMURF2 curbs aerobic glycolysis and cell proliferation in colorectal cancer cells by promoting the ubiquitination and degradation of the carbohydrate response element-binding protein (ChREBP)." (PMID 39697237, 2024). "This interaction between SMURF2 and ChREBP presents a potential target for colorectal cancer management." (PMID 39697237, 2024). "In colorectal cancer, SMURF2 ubiquitinates and degrades the carbohydrate response element-binding protein (ChREBP), curbing aerobic glycolysis and cell proliferation." (PMID 39697237, 2024). "In addition, it has been reported that AAMP is abnormally up-regulated in metastatic CRC and boosts the occurrence of colorectal cancer by inhibiting SMURF2-mediated RhoA liquefaction and degradation." (PMID 37501187, 2023). "Furthermore, it has been recently reported that Akt inhibits the expression of Smurf2 in colorectal cancer cell lines." (PMID 35538534, 2022). "Thus, in summary, high Smurf2 expression in cancer cells was found to be an independent predictor of better prognosis in patients with primary colorectal cancer and consequent liver metastases." (PMID 35361871, 2022). "Notably, the natural compound schisandrin B has been reported to upregulate Smurf2 protein levels in colorectal cancer, while curcumin induces NLRP3-dependent pyroptosis in non-small cell lung cancer (NSCLC) (ncells by inhibiting Smurf2 ubiquitin ligase activity." (PMID 40978141, 2025). "A depletion of SMURF2 results in an upregulation of SIRT1, which fosters the formation and growth of colorectal cancer both in vitro and in vivo." (PMID 39697237, 2024). "We also tested another colorectal cancer cell line, SW480, in which overexpression of Smurf2 similarly reduced HIF-1α expression level under hypoxia." (PMID 34611473, 2021). "To confirm the interaction between Smurf2 and HIF-1α, we performed a co-immunoprecipitation assay in the HCT116 colorectal cancer cell line." (PMID 34611473, 2021). "We then selected the 4 colorectal cancer-related genes ADM, DKK1, HAS3 and SMURF2 for quantitative real-time PCR verification." (PMID 23922913, 2013). "Additionally, Smurf2 mediates the degradation of SIRT1, leading to suppressed cell proliferation and tumorigenesis in colorectal cancer." (PMID 40978141, 2025). "Furthermore, SMURF2 interacts with and degrades sirtuin 1 (SIRT1), with its depletion leading to increased SIRT1 levels, promoting colorectal cancer formation and growth." (PMID 39697237, 2024). "Recent studies have shown that SMURF2 interacts with SIRT1 to mediate the degradation of SIRT1, while deletion of SMURF2 expression leads to upregulation of SIRT1, inducing tumor initiation and the invasive metastasis of colorectal cancer in vivo and in vitro." (PMID 37828084, 2023). "To test whether Smurf2 affects the level of HIF-1α, we transfected the HCT116 colorectal cancer cells with a Smurf2-targeting siRNA to decrease its expression." (PMID 34611473, 2021). "However, the correlation between Smurf2 and clinical outcomes has not been determined in patients diagnosed with colorectal cancer and colorectal liver metastases." (PMID 35361871, 2022).
liver fibrosis (10 papers, 2014 to 2025). "Because PROM1 interfered with the molecular association of SMAD7 with SMURF2 and prevented SMURF2-induced SMAD7 ubiquitination and degradation, we conclude that PROM1 is necessary for the prevention of liver fibrosis by negatively regulating TGFβ signaling." (PMID 36038590, 2022). "SMURF2, a kind of E3 ubiquitin ligase, is able to attenuate liver fibrosis by inhibiting the hepatic stellate cell activation." (PMID 33995497, 2021). "Current research confirmed that SMURF2 was related to the progression of multiple fibrotic diseases, including liver fibrosis and kidney fibrosis." (PMID 33849596, 2021). "Accordingly, Smurf2 interacts with Smad7 to suppress TGFβ-mediated fibrosis, including liver fibrosis and tubulointerstitial fibrosis." (PMID 30450046, 2018). "While this protective function of Smurf2 is evolutionarily conserved and well-documented in renal and hepatic fibrosis models, the upstream molecular hierarchy governing Smurf2 stability-particularly within the distinct microenvironment of the failing heart—has remained elusive." (PMID 41457201, 2025). "Our team used a gene chip to screen the genes in the process of rat liver fibrosis model and found that Smurf2 was abnormally expressed in the process of liver fibrosis, which proved that Smurf2 regulates TGF-β signaling pathways to affect the occurrence and development of liver fibrosis." (PMID 35509688, 2022). "Similar to our results, it has been previously reported that the activity of Smurf2 is decreased in human fibrotic liver, and that the hepatic overexpression of Smurf2 attenuates liver fibrosis, indicating that the expression of Smurf2 might play a role in the inhibition of fibrotic response." (PMID 35538534, 2022). "Smurf2 and miR-132 can co-regulate the expression of CTGF, a core mediator of liver fibrosis, to modulate cAMP-PKA-CREB signaling, which in turn regulates the progression of liver fibrosis." (PMID 39113708, 2024). "Furthermore, curcumin was found to inhibit liver fibrosis in rats by a mechanism that may be related to enhanced ubiquitination and proteasomal degradation of SMAD2 by SMURF2." (PMID 37777567, 2023).